P2RX7 (purinergic receptor P2X 7)
Diseases named in the same sentence as P2RX7 in open-access papers (continued):
Sharing a sentence is not in itself a finding about the gene and the disease.
cancer (194 papers, 2008 to 2026). A tumor composed of atypical neoplastic, often pleomorphic cells that invade other tissues. "Patients with low PANX1 expression in cancer cells or patients carrying P2RX7 polymorphism (E496A/rs3751143) had a better response to adjuvant chemotherapy associated with unfavorable survival outcomes." (PMID 38195677, 2024). "Collectively, these studies provide the conceptual framework for developing new humanized mice lines to explore other human P2RX7 SNPs, some of which have been associated with conditions such as inflammatory and bone disorders, infectious disease and cancer." (PMID 37175933, 2023). "Studies have revealed that P2RX7 gene polymorphisms have been associated with various chronic pains, including arthralgia, diabetic neuropathic pain, and cancer pain." (PMID 36400869, 2023). "Emerging evidences have highlighted that widely expressed P2RX7 is closely associated with a variety of physiological and pathological processes, including inflammation, immune response, pain, neuronal disorder, as well as cancer." (PMID 36803784, 2023). "Therefore, we conducted a comprehensive meta-analysis and systematic review to explore the relationship between P2RX7 rs3751143 polymorphism and the risk of cancer." (PMID 33501930, 2021). "Although several mutations in the P2RX7 gene have been reported to impair pore function, our data show that switching to E200 exposed nfP2X7 can provide a fast-adaptive mechanism to protect cancer cells from high ATP exposure." (PMID 30087439, 2019). "Supporting this, P2RX7 signaling is a key modulator of cancer cell metabolism, by increasing glucose uptake, glycolytic enzymes and glycogen stores." (PMID 36993971, 2023). "It resembles the overexpression of P2RX7 on different cancer cells, where stimulation of this receptor provides significant pro-survival benefits, including increased growth, migration and invasion, and the Warburg effect (reviewed 41)." (PMID 37291185, 2023). "In any case, the studies have been consistent in showing that IL-18 release in an immune-P2RX7-dependent manner is highly antitumoral, and suggesting that boosting the P2RX7/IL-18 pathway is promising for several types of cancer." (PMID 37298187, 2023). "The P2RX7 has been the most studied of the purinoreceptors in regard to cancer proliferation and thus appears to be the most promising avenue for therapeutics." (PMID 37241023, 2023). "Using MDA-MB-435s cells, which expressed P2rx7 mRNA, and the P2X7 antagonist, A-438079, the first of these studies established a role for P2X7 in cancer invasiveness, as a model of metastasis." (PMID 37175933, 2023). "Another explanation is that MMP2-dependent cleavage of P2RX7 enables cancer cells to evade P2RX7-mediated cytotoxicity." (PMID 36803784, 2023). "Typical features of TME like hypoxia and acidosis can modulate cancer metabolism as well as P2RX7 function." (PMID 36803784, 2023). "Preclinical studies point towards strong antitumor efficacy of the P2RX7/IL-18 axis in several types of cancers." (PMID 37298187, 2023). "Given that the role of P2RX7 on cancer cell death and proliferation has been widely studied, this review will mainly focus on the role of P2RX7 in modulating the antitumor immune response and its potential to constitute a novel antitumoral strategy." (PMID 37298187, 2023). "The observation that P2RX7 expression is downregulated in cancer cells is in contradiction with other studies reporting its expression." (PMID 35454832, 2022). "Purinergic Receptor P2X 7 (P2RX7), a ligand-gated ion channel receptor, is overexpressed in several cancers and is expressed differently in many tissues." (PMID 34439196, 2021). "For example, P2RX7 expression is known to be increased in chronic lymphocytic leukemia as well as in cancers originating from various organs including breast, prostate, thyroid, colon and liver." (PMID 34768902, 2021).
cancer (continued). "It was reported that P2RX7 increased cancer invasiveness and metastasis and was adverse prognostic factor." (PMID 32638267, 2020). "Subsequently, P2RX7 signaling has been documented in other physiological and pathological processes including pain, CNS and psychiatric disorders and cancer." (PMID 30003075, 2018). "The existence of a P2RX7-evoked cell death cascade silencing through cholesterol regulation in cancer is an interesting possibility." (PMID 30003075, 2018). "Signalling via the P2×7 (P2RX7 or P2×7R) purinergic receptor is attracting increasing attention as a pathway involved in cancer cell death or proliferation." (PMID 27391069, 2016). "This may be because the reduction in Glu intake caused by sh-TGM2 was compensated by exogenous Glu, alleviating the energy needs of cancer cells and resulting in a moderate decrease in P2RX7 activity." (PMID 41469519, 2025). "Finally, the potential of targeting the P2RX7/IL-18 pathway in combination with classical immunotherapies to fight cancer is discussed." (PMID 37298187, 2023). "Moreover, increase of intracellular calcium levels following P2RX7 activation has been shown to promote cancer cell survival via mitochondrial ion homeostasis, calcineurin activation and NFAT translocation into the nucleus." (PMID 37298187, 2023). "P2RX7 is a ligand-gated transmembrane channel that has attracted increasing attention in cancer." (PMID 36803784, 2023). "Considering that hypoxia is a key feature of cancer, including OS, we examined whether P2RX7 plays a role in the regulation of cell biological behaviors and glucose metabolism under hypoxia." (PMID 36803784, 2023). "The correlation between P2RX7 and cancer metabolic reprogramming has been discussed in a review." (PMID 36803784, 2023). "During evolution, and especially in cancer cells, to maximize P2X7R-mediated trophic advantages and mitigate the dire effects caused by uncontrolled macropore-opening, single nucleotide polymorphisms (SNPs), and splicing variants of the P2RX7 gene originated." (PMID 35075119, 2022). "Remarkably, P2RX7 exerts dual activity in most cancers depending on its degree of activation." (PMID 36589747, 2022). "The CYP2D6*10 SNP is relevant to tramadol pharmacokinetics and opioid dose requirement, while SNPs within UGT2B7 (rs7439366), ABAT (rs1641025), and P2RX7 (rs1718125) have demonstrated some level of potential clinical relevance to cancer pain pharmacogenomics in Asian patients." (PMID 36422103, 2022). "Later in the process of tumorigenesis, P2RX7 overexpression may, on the other hand, help cancer cells to invade, metastasize and resist drugs." (PMID 34768902, 2021). "Hence, a successful cancer treatment with P2RX7 antagonists should, ideally, selectively target cancer cells whilst leaving the host immune response unscathed." (PMID 30003075, 2018). "Given that MMP-2 inhibition can re-open the P2RX7 LP in cancer cells and effectively switch on the LP-associated cell death pathway, it might be possible to develop a new generation of cancer therapeutics promoting this P2RX7 LP formation." (PMID 30003075, 2018). "Perhaps the appropriate metaphor for P2RX7 in cancer would be that of the sword and the shield, where the sword may be blunted through receptor blockade but at the expense of lowering the shield hand." (PMID 30003075, 2018). "Among the P2Rs, a special role in cancer is played by the P2×7 receptor (P2RX7 or P2×7R)." (PMID 27391069, 2016). "Interestingly, P2RX7 is considered to be a critical modulator in cancer metabolic reprogramming." (PMID 36803784, 2023). "Moreover, P2RX7 activation also promotes cytokine release, angiogenesis, and adaptation to serum deprivation, thereby favoring cancer cell survival." (PMID 36589747, 2022).
cancer (continued). "Just as a massiveresearch attack on cancer genetics in the 1980s is now paying dividends in terms ofdrug treatment, so the genetic description of key signalling molecules and mediatorsin the pain system has provided many new targets (e.g., P2RX7,SCN9A) for analgesic drugs that are under development." (PMID 18654615, 2008). "P2rx7-mediated calcium signaling has been shown to trigger the activation of intracellular pathways, including MAPK and PI3K/AKT, critical for cancer proliferation and survival." (PMID 39859313, 2025). "P2RX7 activation in macrophages and DCs releases NLRP3 to increase IL-1β and IL-18 production and NLRP3 has pro- and anti-tumorigenic roles in cancers based on cytokine quantity." (PMID 36741002, 2023). "It has been shown that the ATP/P2RX7 axis leads to the activation of MAP kinases (ERK1/2, p38, JNK), B kinases (PKB, Akt) and PKC involved in cell proliferation in several types of cancer, in mouse and human models." (PMID 37298187, 2023). "The ionotropic ATP receptor P2RX7, (P2X7) is overexpressed in osteocarcinoma and participates to several cancer hallmarks including proliferation, migration, invasion and EMT." (PMID 33117152, 2020). "Contrarily, six ion channels are overexpressed in cancers and promote the activity of Wnt pathway (TRPC5, TRPV4, TRPM4, TRPM8, P2RX7, and ASIC1a)." (PMID 33117152, 2020). "To assess the role of nfP2X7 in cancer cell survival, we transfected three cell lines, devoid of P2X7 pore function and possessing nfP2X7 (PC3, DU145 and LNCaP), with three P2RX7-targeting siRNAs and measured the effect on cell viability." (PMID 30087439, 2019). "We have selected five PCGIs (IGF2, SLC16A12, SOX11, P2RX7 and MYOD1) from cancer and inflammation/age related panels." (PMID 27259265, 2016). "P2RX7 signaling activates the NLRP3 inflammasome, which in turn induces the secretion of active IL-1β, this cytokine playing an important role in the amplification of an efficacious anti-cancer immunity." (PMID 33806300, 2021). "We also demonstrated a clear reduction of metastatic colonization of organs when cancer cells did not express the P2rx7 gene." (PMID 32825056, 2020). "The resulting heatmap showed that in the majority of malignancies, TILs were significantly correlated with multiple representative ICD mediators, such as CALR, LRP1, ANXA1, FPR1, TLR3, IFNAR1, PANX1, and P2RX7." (PMID 33299118, 2020). "Although P2RX7 siRNA significantly reduced L4 binding in SK-MEL-5, it did not have an effect on cell viability, suggesting that nfP2X7 but not WT P2X7 is required for cancer cell survival." (PMID 30087439, 2019). "In this context of cancer cell targeting, the ‘non-functional' P2RX7 (nfP2RX7) is the subject of numerous patents for epitope-specific antibody-based therapy for several cancer types." (PMID 30003075, 2018). "While a loss-of-function allele of purinergic receptor P2X, ligand-gated ion channel, 7 (P2RX7) failed to affect cancer-specific survival, its presence did correlate with an increase in Treg infiltration." (PMID 26369701, 2015). "P2rx7(P2X7R) is believed to have the function of an inflammatory regulator, which can affect the regulation of the body’s immune system, influence the occurrence of inflammation and cancer development, and is one of the key genes in the body’s immune regulation." (PMID 41562058, 2025). "In addition, a non-functional form of P2RX7 that lacks macropore activity has been reported in several types of cancers including lung and glioblastomas." (PMID 37298187, 2023). "For example, we were unable to detect P2RX7 expression on A549 cells when using the monoclonal antibody characterized by Buell, whereas the use of a commercial polyclonal antibody by other authors detected its expression on various NSCLC (including A549) and SCLC cancer cell lines." (PMID 35454832, 2022).
cancer (continued). "Furthermore, as P2RX7 ablation eliminated gelatinase activity in vivo, P2RX7 antagonists could be a good alternative to highly toxic MMP inhibitors in treatments of inflammation and cancers." (PMID 30003075, 2018). "Although SLC11A1 shows excellent immunological prognostic value in other cancers, our K-M curves show better survival for high-expression groups of GBP2, P2RX7, and HCLS1 but not SLC11A1 in EC." (PMID 41007849, 2025).
infection (68 papers, 2011 to 2026). The state of being infected such as from the introduction of a foreign agent such as serum, vaccine, antigenic substance or organism. "P2RX7 knockout mice were more susceptible to infection and had an impaired Th1 response differentiation." (PMID 34795692, 2021). "While previous studies have focused on the effects of loss of function of P2RX7, we show that direct potentiation of the channel enhances host control of infection." (PMID 30693866, 2019). "The aim of this study was to assess if there were differences in allelic and genotypic frequencies of a loss-of-function SNP of ADORA2A (rs2298383) and a gain-of-function single nucleotide polymorphism (SNP) of P2RX7 (rs208294) in the severity of SARS-CoV-2-associated infection." (PMID 38892324, 2024). "Cluster 1 which represents genes that are mostly reduced through the entire course of infection includes many metabolism related genes (e.g., Aldh2, Acad12, Acad10, P2rx7, Ldhb and others)." (PMID 39920132, 2025). "We confirmed the intracellular presence of P2RX7 in our feeder cells as well as an increase in mitochondrial activity in the presence of P2RX7 in our MVA-infection model." (PMID 38711513, 2024). "In summary, we report that presence of P2RX7 significantly alters the energy metabolism of the cells by increasing the availability of mitochondrial ATP after MVA infection." (PMID 38711513, 2024). "We demonstrate that cells expressing a functional P2RX7 seem to handle MVA infections better due to prolonged active cell metabolism and increased energy levels resulting in increased overall cell fitness and delayed apoptotic cell death." (PMID 38711513, 2024). "The presence of active P2RX7 in feeder cells during MVA infection led to a dramatic increase in CD8+ T cell activation and enhanced expression of SIINFEKL/H2-Kb complexes on murine antigen-presenting cells via cross-presentation." (PMID 38711513, 2024). "We also showed that CM P2RX7 transfected cells allowed the secretion of significantly higher amounts of inflammatory cytokines pre- as well as post-infection, demonstrating that the presence of functional P2RX7 modulates other signaling pathways as well." (PMID 38711513, 2024). "In contrast, basal secretion of ATP by these cells (extracellular ATP level) was less or comparable when infected with MVA, while cells with inactive P2RX7 released significantly higher amounts of ATP into the supernatant after MVA infection." (PMID 38711513, 2024). "In sum, we demonstrated that the presence of functional P2RX7 in feeder cells aids in improving antigen cross-presentation upon MVA infection." (PMID 38711513, 2024). "P2RX7 is a ligand-gated cation channel activated by extracellular ATP, which is found at sites of infection and injury." (PMID 30693866, 2019). "Furthermore, functional P2RX7 in feeder cells resulted in a delayed but also prolonged antigen expression after infection." (PMID 38711513, 2024). "Interestingly, infection with the clinical isolate UT205 exclusively induced the expression of the P2RX7 gene, which with other genes such as CFLAR and BIRC3, showed enrichment in processes of cell death by necrosis and necroptosis." (PMID 32391286, 2020). "Further understanding of the mechanistic basis for P2RX7-mediated mycobacterial control, as well as ways in which inflammasome activation can be modulated at discrete points in infection, may lead to new approaches to host-directed therapies." (PMID 30693866, 2019). "Furthermore, during an inflammatory response following infection, interferon-γ is produced which activates macrophages and increases expression of the P2RX7." (PMID 22548201, 2012). "Among the 1,451 genes whose expressions were specifically altered in CEF after infection, some were involved in immune-related functions, while others, such as the significantly upregulated SLBP, P2RX7, GGT5, and RNF213, could promote viral particle replication or enhance the effect of infection." (PMID 38299864, 2024).
neurodegenerative disease (43 papers, 2008 to 2026). A disorder of the central nervous system characterized by gradual and progressive loss of neural tissue and neurologic function. "This understanding enhances the knowledge of how αSyn and P2RX7 interactions take place, potentially contributing to neurodegenerative diseases, and could be instrumental in developing future preventive and therapeutic approaches." (PMID 40315262, 2025). "Thus, P2RX7 modulation is a promising option for treatment of neurodegenerative diseases." (PMID 40948939, 2025). "Additionally, the elevated HSP90AA1 and P2RX7 levels could in turn lead to tau hyperphosphorylation and neuroinflammation, two critical contributors to this neurodegenerative disease." (PMID 38360834, 2024).
psychiatric disorder (15 papers, 2009 to 2025). A disorder characterized by behavioral and/or psychological abnormalities, often accompanied by physical symptoms. "The human P2RX7 gene is located at the chromosome position also associated with inflammatory and psychiatric disorders." (PMID 32848594, 2020). "One of the genes of interest, P2RX7 that is associated with psychiatric diseases, was significantly reduced in expression after LPS stimulation in SCZ patients." (PMID 29138398, 2017). "Although several genes in close proximity to P2RX7 in chromosomal region 12q24.21-33 are associated with SCZ and it is linked to other psychiatric diseases, our study shows an effect of P2RX7 in SCZ." (PMID 29138398, 2017). "In addition to metabolic disturbances, P2RX7 has also been implicated in psychiatric disorders." (PMID 28737528, 2017). "Alterations in receptor function caused by non-synonymous single nucleotide polymorphisms (SNPs) in the human P2RX7 gene have been associated with various diseases including bone disorders, infectious disease, inflammatory and cardiovascular disorder, malignancies, and psychiatric disorders." (PMID 27858314, 2017). "A brief overview of pathway-level information highlights the mechanistic relevance of P2RX7 as a molecular hub mediating neuroinflammatory responses that may contribute to the onset and progression of psychiatric disorders, by linking early-life stress, inflammation, and affective dysregulation." (PMID 40429831, 2025). "However, there is increasing evidence that P2RX7 also plays a pivotal role in central nervous system pathologies and in psychiatric disorders, where the link with inflammation is not always clear." (PMID 29642926, 2018).
neurological diseases (14 papers, 2009 to 2025). "Notably, many of these DEGs have been associated previously with neurological disease including SPHK2 (sphingosine kinase 2); P2RX7 (purinergic receptor P2X 7); SMPD4 (sphingomyelin phosphodiesterase 4); ASAH1 (N-acylsphingosine amidohydrolase 1)." (PMID 38625017, 2024).
inflammation (12 papers, 2011 to 2026). Aberrant reaction of the microcirculation characterized by movement of fluid and leukocytes from the blood into extravascular tissues. "Accordingly, genetic ablation of P2rx7 resulted in reduced IL-1ß production and alleviated cigarette smoke (CS)-induced airway inflammation in mice." (PMID 35676684, 2022).
cardiovascular diseases (11 papers, 2009 to 2024). "Following a literature review, we chose four RBPs (HSPA1A, ZFP36, TRIM21, and P2RX7) that play important roles in the development of cardiovascular diseases for further co-expression analysis." (PMID 37180137, 2023).